RNU6-65P (RNA, U6 small nuclear 65, pseudogene)
Synonyms: RNU6-65
Gene: Small nuclear RNA gene on chromosome 13 (51,565,412 to 51,565,509, forward strand). Ensembl gene ENSG00000252141.
Homologues: Orthologues: chimpanzee U6 (98% identical), rabbit U6 (71% identical), guinea pig U6 (70% identical), dog U6 (63% identical), rabbit U6 (57% identical), rabbit U6 (56% identical), rabbit U6 (53% identical), rabbit U6 (52% identical). Paralogues in human: RNU6-1024P (77% identical), RNU6-1 (76% identical), RNU6-116P (76% identical), RNU6-12P (76% identical), RNU6-13P (76% identical), RNU6-17P (76% identical), RNU6-18P (76% identical), RNU6-2 (76% identical), RNU6-25P (76% identical), RNU6-26P (76% identical), RNU6-32P (76% identical), RNU6-338P (76% identical), and 1283 more.